ANKRD65 (ankyrin repeat domain 65)
Tractability: No criterion of Open Targets' tractability assessment is met for any kind of drug.
Gene: Protein-coding gene on chromosome 1 (1,415,637 to 1,421,769, reverse strand). Ensembl gene ENSG00000235098.
Subcellular location (Human Protein Atlas): Microtubules; Nucleoplasm; Primary cilium; Cytokinetic bridge; Mitotic spindle; Primary cilium tip
Genetic constraint (gnomAD): Loss-of-function variants: 23 observed, 12.57 expected, observed/expected ratio (o/e) 1.83, 90% interval 1.25 to 1.97. The synonymous counts are far from expectation, so gnomAD's model fits this gene poorly and the ratio says little. Missense variants: 527 observed, 400.91 expected, observed/expected ratio (o/e) 1.31, 90% interval 1.22 to 1.41. Synonymous variants: 263 observed, 195.84 expected, observed/expected ratio (o/e) 1.34, 90% interval 1.21 to 1.49.
Homologues: Orthologues: chimpanzee ANKRD65 (92% identical), macaque ANKRD65 (91% identical), dog ANKRD65 (73% identical), mouse Ankrd65 (63% identical), rat Ankrd65 (63% identical), Drosophila melanogaster rols (23% identical). Paralogues in human: CTTNBP2 (26% identical), TANC2 (25% identical), TANC1 (23% identical), ANKRD63 (13% identical).